CD4 (CD4 molecule)
Diseases named in the same sentence as CD4 in open-access papers (continued):
Sharing a sentence is not in itself a finding about the gene and the disease.
psoriasis (continued). "Our data demonstrate that TSP-1-CD47 interaction or the incubation with anti-CD47 mAb inhibits the differentiation of Th17 cells and favors CD4+ T cells differentiation into Treg cells from psoriasis patients." (PMID 31214201, 2019). "The expression of miR-210 is increased in CD4+ T cells from psoriasis patients and negatively affects FOXP3 expression, thereby inhibiting immune regulatory functions." (PMID 31333659, 2019). "As IL-21 was mainly expressed in CD4+ T cells in the lesional skin of psoriasis patients, we then investigated the IL-21 expression in CD4+ T cells in PBMCs." (PMID 31440249, 2019). "One study reported an increase of Tfh17 CD4+ T cells in peripheral blood of psoriasis patients that correlated with disease activity." (PMID 30915067, 2019). "We found that the proportion of Th17 cells in CD4+ T cells was higher, whereas the proportion of Treg cells in CD4+ T cells was lower in psoriasis patients, compared with the healthy individuals." (PMID 31440249, 2019). "Examples of CD4+ T cell effector functions from other chronic inflammatory conditions (psoriasis and Crohn's disease) are selected to contrast and discuss our current knowledge in the field of RA." (PMID 30915067, 2019). "The changes in the immunological status are critical in the induction of inflammatory diseases such as psoriasis and an increase in the ratio of CD4+/CD8+ T cells has been found in early as well as in late phases of psoriasis." (PMID 31710084, 2019). "Our results showed that IL-21R is highly expressed in PBMCs and in the lesional skin of psoriasis patients, and that IL-21 can promote CD4+ T cell proliferation and Th17 cell differentiation and also the secretion of IL-17A and IL-22." (PMID 31440249, 2019). "VD3 analogues exert their immunomodulatory effect by enhancing the immunosuppressive activity of CD4+ Tregs22 and show more persistent action against psoriasis than BDP23." (PMID 31705000, 2019). "Our results showed that more CD4+ T cells were proliferated after being stimulated with IL-21, both in psoriasis patients and healthy individuals." (PMID 31440249, 2019). "These assays showed that the anti-CD47 mAb clearly prevented the activation of CD4+ T cells during Ag presentation in cells from psoriasis patients." (PMID 31214201, 2019). "The percentage of CCR6+CXCR3− cells within the CD4+ TEM subset in the total cohort of psoriasis and PsA patients significantly correlated with serum concentration of CRP." (PMID 31350460, 2019). "Activated Th1 and Th17 T cells (CD4+ T cells) and CD8+ T cells, as well as increased levels of cytokines such as IL-17, IL-23, TNF-α and IL-27, have been directly implicated in psoriasis immunopathogenesis." (PMID 31130981, 2019). "Psoriasis is a Th1 and Th17 cell-mediated disease, and the presence of CD4+ Th1 cells is increased in lesional plaques, as well as the levels of cytokines consistent with the Th1 profile, such as IFN-γ and TNF-α." (PMID 30987186, 2019). "CD4+ T cells were isolated from the peripheral blood mononuclear cells (PBMCs) from the psoriasis patients and healthy individuals and then treated with or without IL-21 for 3 days." (PMID 31440249, 2019). "Overall, consistent with the findings of the lesional skin, IL-21 and its receptor were highly expressed in the CD4+ T cells of PBMCs of psoriasis patients." (PMID 31440249, 2019). "Peripheral CD4+ T cells and circulating primary DCs from psoriasis also expressed lower levels of CD47 compared to controls." (PMID 31214201, 2019). "In contrast to these observations in PBMCs and total CD4+ T cells, naïve CD4+ T cells from psoriasis patients exhibit methylation profiles that are mostly comparable to healthy controls." (PMID 31333659, 2019). "Conversely, treatment with IL-23p19 antagonists achieves a relatively long-term response in psoriasis patients, which can be partly explained by these agents promoting trans-differentiation of Th17 cells into CD4+ Tregs by blocking the action of IL-231." (PMID 31705000, 2019).
psoriasis (continued). "Our result revealed that an increased number of CD4+ T cells secrete IL-21 and express IL-21R in the PBMCs derived from psoriasis patients." (PMID 31440249, 2019). "To evaluate the functional role of CD47 and TSP-1 in psoriasis inflammatory response we performed Th17 and Treg differentiation assays on peripheral CD4+ T cells from psoriasis patients and healthy controls." (PMID 31214201, 2019). "Psoriasis is an immune inflammatory disease, the pathogenesis of which involves a variety of immune cells, such as neutrophils, dendritic cells, and CD4+ T cells." (PMID 31861934, 2019). "In the present study, we characterized the enrichment of psoriasis SNPs in chromatin states across immune cells/tissues, and then integrated the psoriasis SNPs and histone marks peaks in relevant CD4+ T cells." (PMID 29715312, 2018). "Traditionally, much attention has been given to differentiated CD4+ T-cell subsets across chronic inflammatory diseases, including psoriasis." (PMID 30555460, 2018). "Recently, a distinct subtypes of CD4+ T cell, Th17 cells, have emerged as a key player in psoriasis pathogenesis, which are more highly expressed in psoriatic dermis and make up more than 50%, even 90% of the CD4+ population in psoriatic lesions." (PMID 29523162, 2018). "In fact, our study shows that IL-17A from CD8+ T cells, CD4+ T effectors, and CD4+ Tregs were also higher in psoriasis samples compared to controls." (PMID 30054515, 2018). "The shift towards a Th1 dominated cytokine profile is supported by elevated TNF-α and IL-17A production from CD4+ T effector cells in psoriasis samples." (PMID 30054515, 2018). "A recent study found that increased miR-138 regulates the balance of Th1/Th2 through inhibiting RUNX3 expression in CD4+ T cells in psoriasis." (PMID 29715312, 2018). "Our study added novel findings that topical MaR1 inhibits IMQ-induced psoriasis in an animal model through inhibition of IL-17A production by both γδTCRmid+ and CD4+ cells in the skin." (PMID 29615641, 2018). "The inhibition of RUNX3 reduced the relevant cytokines levels, and decreased the frequency of Th17 and Th22 cells in CD4+ T cells from psoriasis patients." (PMID 29715312, 2018). "Previous studies have shown that induction of endogenous CD4+CD25+Foxp3+ Tregs or reversal of Th17/Treg imbalance ameliorates IMQ-induced psoriasis in mice." (PMID 30258447, 2018). "Th17cells and Treg cells also represent two CD4(+) T-cell subsets, and are centralplayers in the pathogenesis of psoriasis." (PMID 29630472, 2018). "This phenomenon reflected a negative regulation of immune response by CD4+/PD-1+ lymphocytes in the pathogenesis of psoriasis and RA." (PMID 30069490, 2018). "All three psoriasis subtypes had significantly lower IL-13 from CD4+ T effector cells compared to healthy control skin." (PMID 30054515, 2018). "CD4+CD25+Foxp3+ Tregs can differentiate into IL-17A-producing Th17 cells in patients with psoriasis." (PMID 30258447, 2018). "CD4+ T cell recognition of Candida and Malassezia antigens can be very different, as demonstrated in psoriasis." (PMID 29675414, 2018). "The decrease in CD4+ T effector-derived IL-13 seen in all subtypes of psoriasis is consistent with previous studies and suggests a shift in the Th1-Th2 axis." (PMID 30054515, 2018). "The role of T cells in the pathogenesis of psoriasis has been well described, and both CD4+ T cells (T helper cells, Th) and CD8+ T cells (cytotoxic T cells, Tc) seem to be critical in the development of the skin lesions." (PMID 29316717, 2018). "Flow cytometry analysis revealed a shared increase in the percentage of CD4+ T regulatory cells in all psoriasis subtypes relative to controls, whereas distinct psoriasis subtypes displayed differences in IL-17A, IFN-gamma, and IL-22 production." (PMID 30054515, 2018). "Psoriasis is a CD4+ T cell-medicated autoimmune and inflammatory cutaneous disorder, which affects 2% to 3% of the world population." (PMID 29686529, 2018).
psoriasis (continued). "More recently, a psoriasis mice model was developed based on an autoimmune mechanism, wherein injection of IL-17-producing CD4+ T cells recognizing desmoglein 3 as autoantigen was able to develop psoriasis-like lesions." (PMID 29316717, 2018). "We discovered in primary CD4+ T cells that the majority of psoriasis PFVs are resided in non-coding genome regions, especially in gene enhancer elements." (PMID 29715312, 2018). "Both γδ T cells and CD4+ Th17 cells are IL-17-producing effector cells that drive human psoriasis and the IMQ-induced model of psoriasiform inflammation." (PMID 28469254, 2017). "The majority of infiltrating CD4+ T cells in psoriasis are Th1 cells characterized by their production of Th1 cytokines such as interferon-γ (IFN-γ), interleukin (IL)-2 and IL-12." (PMID 29232931, 2017). "In our study, the negative correlations between the percentages and absolute number of CD4+ T cells and severity of psoriasis measured by PASI and IGA were observed." (PMID 29180838, 2017). "Our results showed that NTP treatment can treat psoriasis-like skin inflammation through inhibition of CD4+ T cell differentiation, suppressed pro-inflammatory responses, and induction of PD-L1 expression." (PMID 29138509, 2017). "Aberrant IL-17 producing CD4+ helper T-cells (Th17) have been identified as pivotal for the pathogenesis of certain inflammatory autoimmune disorders, including psoriasis." (PMID 28672038, 2017). "The γδ T cells in the skin-draining lymph node of psoriasis produce approximately 10 times more IL-17A and IL-22 than CD4 T cells." (PMID 28761880, 2017). "Double-staining immunofluorescence further identified the higher infiltration of CXCR5+CD4+ T cells in lesions of psoriasis patients." (PMID 27774460, 2016). "To investigate the function of NRIP1 in regulating the secretary profile of CD4+ T cells, we isolated CD4+ T cells from psoriasis patients and used siRNA to silence NRIP1 (siNRIP1) expression." (PMID 27708240, 2016). "We have recently reported that CCR4+ CD4+ T cells are increased in the circulation of patients with psoriasis proportionally with the increased severity of the cutaneous manifestations of the disease expressed as PASI (Psoriasis Area and Severity Index) score." (PMID 27595115, 2016). "The newly found subpopulations of CD4+ T cells, such as Th17, Th22, and regulatory T cells, have enriched our understanding of the immune state of psoriasis." (PMID 27774460, 2016). "The autoimmune nature of psoriasis has been established only recently by the discovery of the role of cathelicidin (LL37), keratinocyte-derived antimicrobial peptide, as an autoantigen for both CD8 and CD4 autoreactive T cells in psoriasis patients." (PMID 27595115, 2016). "CD4+ T cells are critical component of immune system and have been demonstrated to play a central role in the pathogenesis of psoriasis." (PMID 27774460, 2016). "This links CD4+ T helper cells recirculating between skin and blood with the clinical manifestations of psoriasis." (PMID 27595115, 2016). "In our models we observed infiltration of neutrophils and IFNγ-producing CD4+ T cells to the skin, which is similar to human psoriasis." (PMID 26701909, 2015). "Although psoriasis was initially classified as a Th-1-polarized disease, a clear role for CD4+ T cells that produce IL-17A and IL-22 (Th-17 and Th-22 cells) has been established in recent years, primarily at lesional sites, but also in the blood." (PMID 23468834, 2013). "Taken together, CD4+CD25+T cells in psoriasis patients are dysfunctional, and photochemotherapy restores those dysfunctional cells to the normal level in this study." (PMID 23365685, 2013). "IL-22, another important cytokine for psoriasis pathogenesis, can be produced by CD4+ T and CD8+ T cells." (PMID 23468834, 2013). "We assessed CD4+CD25+ (Forkhead box protein 3) Foxp3+ Treg in the peripheral blood of psoriasis patients before and after bath-PUVA therapy." (PMID 23365685, 2013).
psoriasis (continued). "Specifically, the CD4+CD25high Foxp3+ cells are more prone to conversion in patients with severe psoriasis suggesting that they play a role in the disease." (PMID 24062996, 2013). "The immunomodulatory effects of cortisol in pathogenesis of psoriasis are highlighted by the fact that the earliest immunologic event in new psoriasis lesions is accumulation of CD4+ and CD8+ T-helper lymphocyte and extravasation of T-helper lymphocytes." (PMID 24288511, 2013). "In this study, we explored changes in cytokine production by memory CD4+ T cells as well as in the differentiation of naïve T cells to helper T cell (Th) 1, Th2, or Th17 cells in psoriasis patients treated with ustekinumab." (PMID 23251632, 2012). "In contrast, CD4+ T cell counts were slightly lower in psoriasis patients than in controls (742 ± 276 vs. 843 ± 283; p = 0.125)." (PMID 22493730, 2012). "We used MZ twins discordant for psoriasis to search for genome-wide differences in DNA methylation and gene expression in CD4+ and CD8+ cells using Illumina's HumanMethylation27 and HT-12 expression assays, respectively." (PMID 22291603, 2012). "Another animal model based on T-cell transfers to pathogen-free scid/scid mice (CD4+/CD45RBhi model) presents an inflammatory cytokine response via dysregulated T-cells with altered keratinocyte differentiation, mimicking human psoriasis." (PMID 23226485, 2012). "Psoriasis is a chronic inflammatory skin disorder whose manifestations are orchestrated by proinflammatory CD4+ T cells that produce either Th1 or Th17 cytokines." (PMID 19707549, 2009). "Clinical studies in psoriasis showed a reduction of peripheral CD4+- and CD8+-T-lymphocytes due to the ability of FAE to induce apoptosis." (PMID 19721818, 2009). "Our fully human CD4 mAb zanolimumab was assessed in Phase I/II clinical trials in rheumatoid arthritis and psoriasis." (PMID 18702090, 2008). "CD8+/CD4+ Tcm cell injection and NF-κB inhibitor or agonist treatment were then used to investigate the role and mechanisms of Trm cells in recurrent psoriasis." (PMID 41737494, 2026). "Furthermore, the relative number of CD4+Foxp3+CD25+ cells showed increases in psoriasis mice treated with anti-IL-2/IL-2 complex as compared to other groups." (PMID 41254515, 2025). "Compared to healthy controls, psoriasis patients exhibited significantly higher infiltration of activated dendritic cells, M0 and M1 macrophages, monocytes, neutrophils, resting CD4+ memory T cells, CD8+ T cells, follicular helper T cells, and regulatory T cells (Tregs)." (PMID 41328434, 2025). "This antagonistic regulatory pattern suggests that CXXC5 and SLFN5 may play complementary roles in balancing CD4+ T cell activation and homeostasis, highlighting their potential functional relevance in psoriasis and other immune-related diseases." (PMID 41328434, 2025). "Next, we similarly studied the immune infiltration in psoriasis and found that M2 macrophages, monocytes, and resting CD4+ memory T cells were significantly elevated in psoriasis, similar to the findings in atopic dermatitis, while resting mast cells were reduced." (PMID 40159643, 2025). "For example, in the imiquimod (IMQ)-induced psoriasis model, enhanced features of psoriatic inflammation are associated not only with increased expression of STAT3, NF-kB, IFN-γ and TNF-α in CD4+ T cells but also activation of lymphocyte-specific protein tyrosine kinase (Lck)." (PMID 40868162, 2025). "Notably, in the CD4+ T cell compartment, the activation marker 4-1BB was upregulated on inflammatory CXCR3+CD4+ T cells in all memory subsets in psoriasis-like conditions compared to the control group, with a more pronounced increase in CD4+ TCM and TTE cells." (PMID 40599782, 2025). "The contribution of CD8+ T cells to epidermal inflammation was further confirmed in two mouse strains through depletion of CD4+ or CD8+ T cells in vivo to explore the indispensable function of CD8+ T in driving the epidermal inflammatory phenotype in psoriasis." (PMID 41162356, 2025).
psoriasis (continued). "This evidence suggests that NKG2A+ CD4+ T cells may play a key immunoregulatory role in the pathological activation of CD4+ T cells in psoriasis." (PMID 41328434, 2025). "CXCL10 appears to be important for leukocyte trafficking that leads to increased tissue inflammation and may be overexpressed in CD4 + T helper 1 (Th1)-mediated inflammatory diseases like multiple sclerosis and psoriasis." (PMID 39924511, 2025). "Interestingly, Th1-like immunosuppressive Tregs depend on IL-12p70 and IFN-γ for their generation, yet enhanced IFN-γ expression in CD4+ T cells characterises the murine psoriasis model." (PMID 40868162, 2025). "An increase in the levels of regulatory T-cells (Tregs) and CD4+ memory T-cells levels was observed, whereas the levels of Th-17, as well as serum IL-17 levels were reduced, suggesting the anti-inflammatory effects of MSCs in the treatment of psoriasis." (PMID 40748586, 2025). "Notably, IFN-γ produced by CD4+ T cells has been recognized as a major contributor to the emergence of guttate psoriasis, while IFN-γ from CD8+ T cells appears to be more influential in the immunopathogenesis of plaque psoriasis." (PMID 40303401, 2025). "Furthermore, IFN-γ and IL-17 derived from CD4+ T cells play a pivotal role in the pathogenesis of guttate psoriasis." (PMID 40303401, 2025). "It is well established that Th17 cells are a major pathologic CD4+ T helper subset in psoriasis." (PMID 40948686, 2025). "Ustekinumab exerts its therapeutic effects by targeting the p40 subunit, which is shared by both interleukin-12 (IL-12) and interleukin-23 (IL-23), two cytokines involved in inflammatory processes and in the activation of natural killer (NK) cells and CD4+ T lymphocytes in psoriasis." (PMID 40731810, 2025). "Adaptive immune cells drive the chronicity of psoriasis through antigen-specific responses and immune memory, encompassing T cell subsets (CD4+, CD8+, γδ T, Th1, Th17, Th22, Th9, Treg, and tissue-resident memory T cells [TRM]), B cells, and regulatory mechanisms." (PMID 40948748, 2025). "We observed that TNF-α-treated HaCaTs-derived exosomes can accelerate the psoriasis process by delivering AGAP2-AS1 to promote CD4+ T cell differentiation towards Th1 and Th17 cells and secretion of more inflammatory factors such as IFN-γ and IL-17A, which affect the immune microenvironment." (PMID 40520230, 2025). "Our previous research demonstrated that AGAP2-AS1 in keratinocytes is involved in the pathogenesis of psoriasis, but its effect on CD4+ T cell differentiation remains unclear." (PMID 40520230, 2025). "Similarly, in psoriasis, CD4+ T cells are activated by dendritic cells presenting self-antigens, releasing proinflammatory cytokines such as TNF-α, IL-17, and IL-22." (PMID 40310305, 2025). "EZH2 was previously shown to relate to keratinocyte proliferation and inflammatory responses in psoriasis, and it may also affect CD4+ and CD8+ T cell differentiation and epidermal stratification, potentially contributing to psoriatic hyperkeratosis." (PMID 40650108, 2025). "Currently, the immune cells closely related to psoriasis are mainly dendritic cells and CD4+ cells." (PMID 39109246, 2024). "To determine whether TBTDC NP-PDT could attenuate the inflammatory response in mice with IMQ-induced psoriasis, we examined the size of the spleen and the number of dendritic cells and CD4+ T cells in the dermis." (PMID 39109246, 2024). "In addition, TAVO101 showed a trend of slightly more efficacious than tezepelumab in inhibiting TSLP-driven proliferation of activated CD4+ T cells in an ex vivo study and in an in vivo study with imiquimod induced psoriasis mouse model." (PMID 39726595, 2024). "Moreover, circulating CD4+ T cells in psoriasis are enriched in TNF-α+ cells compared to healthy controls." (PMID 38642273, 2024). "CD4+ T helper (TH) cells orchestrate skin inflammation in psoriasis." (PMID 38642273, 2024).